ACTRT2 (actin related protein T2)
Synonyms: ARP-T2; ARPM2; FLJ25424; ARPT2; HARPM2
Tractability: No criterion of Open Targets' tractability assessment is met for any kind of drug.
Gene: Protein-coding gene on chromosome 1 (3,021,467 to 3,022,903, forward strand). Ensembl gene ENSG00000169717.
Subcellular location: Cytoplasm, cytoskeleton
Gene Ontology:
Molecular function: protein binding; structural constituent of cytoskeleton
Biological process: cytoskeleton organization
Cellular component: actin cytoskeleton; perinuclear theca; cytoskeleton
Genetic constraint (gnomAD): Loss-of-function variants: 2 observed, 4.74 expected, observed/expected ratio (o/e) 0.42, 90% interval 0.17 to 1.31. That is too few expected variants to judge how well the gene tolerates losing a copy. Missense variants: 488 observed, 522.52 expected, observed/expected ratio (o/e) 0.93, 90% interval 0.87 to 1.01. Synonymous variants: 262 observed, 240.29 expected, observed/expected ratio (o/e) 1.09, 90% interval 0.99 to 1.21.
Homologues: Orthologues: chimpanzee ACTRT2 (99% identical), macaque ACTRT2 (95% identical), dog ACTRT2 (85% identical), pig ACTRT2 (84% identical), rat Actrt2 (81% identical), mouse Actrt2 (81% identical), guinea pig ACTRT2 (80% identical). Paralogues in human: ACTRT1 (75% identical), ACTB (49% identical), ACTG1 (48% identical), ACTA1 (48% identical), ACTA2 (48% identical), ACTG2 (48% identical), ACTC1 (47% identical), ACTBL2 (47% identical), ACTRT3 (45% identical), ACTR1B (41% identical), ACTR1A (41% identical), ACTL9 (38% identical), and 14 more.
Diseases named in the same sentence as ACTRT2 in open-access papers:
ACTRT2 is named in the same sentence as 7 diseases in open-access papers, as found by Europe PMC text mining. Sharing a sentence is not in itself a finding about the gene and the disease. The quoted sentences say what the papers report.
Obesity (2 papers, 2022 to 2023). Accumulation of substantial excess body fat. "Another such gene, ACTRT2, is reported to be localised in the post-acrosomal region of mouse spermatozoa, as well as the post-acrosomal region and midpiece in males with low spermatozoal motility which resulted from obesity." (PMID 37508063, 2023).
male infertility (1 paper, 2020). The inability of the male to effect fertilization of an ovum after a specified period of unprotected intercourse. "Collectively, these results indicated that these proteins AKAP4, ODF1, ODF2, GAPDHS, SPESP1, and ACTRT2 were significantly down-regulated after heat treatment of scrotum, suggesting that these proteins may serve as the biomarkers for scrotal heat treatment-induced male infertility." (PMID 32787870, 2020).
varicocele (1 paper, 2020). A condition characterized by the dilated tortuous veins of the spermatic cord with a marked left-sided predominance. "ACTRT2 expression in the mature spermatozoa of patients with varicocele was previously shown to be up-regulated, in contrast to the results of the ACTRT2 expression obtained in our study." (PMID 32787870, 2020).
tumor (1 paper, 2021). "For example, we found that ATAD1, TBC1D9, and TNNC2 expression are all mediated by transcription factors ACTRT2, MMP23B, and TP73 and methylation sites around MMP23B and TP73; these transcription factors have known functions in tumor suppression or proliferation." (PMID 33684137, 2021).
ACTRT2 also shares sentences with these, for which no sentence is quoted: asthenozoospermia (1 paper); oligospermia (1); renal carcinoma (1).